FOS (Fos proto-oncogene, AP-1 transcription factor subunit)
Diseases named in the same sentence as FOS in open-access papers (continued):
Sharing a sentence is not in itself a finding about the gene and the disease.
melanoma (continued). "For the malignant melanoma cells, PMEL, IFITM1, HSPA1A, DUSP1, FOS and TMSB4X are the shared driver genes across three subtypes in S4 File." (PMID 38096269, 2023). "These analyses show that FOS, NR4A, and ITGB1 genes were significantly higher in older melanoma patients with positive SLNs." (PMID 33373316, 2020). "Our results show that FOS, NR4A, and ITGB1 genes were significantly higher in older melanoma patients with tumor-positive SLNs." (PMID 33373316, 2020). "The potential value of the HOXB7/PBX2→miR-221&222→c-FOS pathway suggests the disruption of the HOXB7/PBX2 complexes, miR-221&222 inhibition or their combination as innovative therapeutic approaches in melanoma." (PMID 23400877, 2013). "Phosphorylation of FOS, another downstream factor of BRAF V600E, promotes FOS binding to the GABPB 5′ UTR, constantly activating GABPB and promoting its binding to the mutant TERT promoter in PTC cells and melanoma cells." (PMID 38278800, 2024). "JQ1 was characterized by induction of inhibitory relationship linking regulators of inflammation (IFNG, IL17A, TGFB2), melanoma biological behavior (EGFR, WNT3A, TEADs, MRTFB), cell-cell interaction (CD44, CCN2), YAP pathway (LLGL2, NSUN6) and main transcriptional regulators (FOS, JUN, FOXM1)." (PMID 36397155, 2022). "Focusing on melanoma, we previously showed that miR-221&222 play a dynamic role regulating proliferation and progression repressing several antineoplastic targets (e.g., p27Kip1/CDKN1B, c-KIT receptor and c-FOS)." (PMID 26912358, 2016). "Surprisingly, the analysis of miR-221&222 and c-FOS levels in the panel of melanoma cell lines did not reveal the expected obvious inverse correlation between microRNAs and their targets." (PMID 23400877, 2013). "However, an EGR1 -like pattern of gene expression was observed for JUN, indicating that the intensity of expression of the EGR1, FOS, IER2, and JUN transcription factor genes could be coregulated at least in some human melanomas." (PMID 39436655, 2024). "Interestingly, TNF-α signalling via the NF-κB pathway was significantly downregulated with a reduction ranging from 7- to 40-fold in expression of some of its prooncogenic target genes (e.g., JUNB, FOS, DUSP1) and melanoma-related genes (e.g., EGR3, NR4A3, CCN1)." (PMID 34497073, 2021). "Our previous results showed that miR-221&222 are key factors for melanoma development and dissemination, as they control the progression of the neoplasia through the down-modulation of several direct targets, as p27Kip1/CDKN1B, c-KIT receptor and c-FOS, all playing antineoplastic functions." (PMID 26912358, 2016). "Depletion studies using the DepMap database revealed that silencing FRA1, but not other FOS family members (FOS, FOSB, FRA2), significantly reduces cell viability in melanoma and across multiple cancer types." (PMID 41286309, 2025).
colon carcinoma (32 papers, 2012 to 2025). "According to PubMed literature review, Snail, SOX17, HNF3β, c-FOS, and RORα-1 have been confirmed to be associated with colon cancer." (PMID 34337040, 2021). "High levels of RPA2 expression have been associated with adverse disease progression and it may also be a therapeutic potential target for treating colon cancer itself, while FOS gene expression has been found to be associated with progression of pancreatic cancer tumors." (PMID 34585118, 2021). "Our results uncovered that NANOG, rather than KLF4, OCT4, and SOX2, was significantly up-regulated in FOS-overexpressed colon cancer cells." (PMID 38233377, 2024). "Only 5 of the 14 transcription factors (Snail, SOX17, HNF3 β, c-FOS, and RORα-1) are involved in the occurrence and development of colon cancer, consulting the literature through the PubMed database." (PMID 34337040, 2021). "In colon cancer cells, suppressing FOS and β-catenin can effectively inhibit proliferation of cancer cells." (PMID 33373316, 2020). "PAF can rapidly induce the expression of the AP-1 subunit c-FOS and the phosphorylation on the activating sites (Ser63 and Ser73) of c-Jun in fibroblasts and in human colon carcinoma cells." (PMID 30832675, 2019). "Additionally, PCIF1 has been reported to regulate colon cancer growth and response to anti-PD-1 by stabilizing cancer-promoting gene mRNAs, such as FOS, IFITM3, and STAT1, through m6Am modifications." (PMID 39451207, 2024). "The expression of c-FOS is associated with the metastasis and TNM stage of colon cancer." (PMID 34337040, 2021). "Notably, upon analysis of bulk RNA in the 32 colon cancer patient samples, we found that ciRS-7 was significantly positively correlated with FOS (r = 0.84, P < 0.0001), NR4A3 (r = 0.80, P < 0.0001) and PIK3CD (r = 0.40, P = 0.02)." (PMID 32917870, 2020). "The induction of tumour suppressor DACOR1 in colon cancer cells restores DNA methylation of thousands of CpG dinucleotides at hypomethylated sites in colon tumours including intergenic regions, promoters and gene bodies of oncogenic transcription factors such as FOS and JUN." (PMID 31430887, 2019). "Both FOS and nucleolin are involved in the regulation of cell proliferation as their decreased expression has been related with reduced proliferation capacity of cancer cells including colon cancer cell lines." (PMID 25056133, 2014). "In colon cancer, the expression of cheRNA DACOR1 is inhibited, and induction of DACOR1 leads to the remethylation of CpG islands at FOS and JUN promoter sites, thereby affecting the development of colon cancer." (PMID 33937246, 2021). "Interestingly, FOS and JUN are present in gained enhancers in colon cancer, leading to implication in the differentiation, proliferation and apoptosis of colon cancer cells." (PMID 25477382, 2015).
osteoporosis (32 papers, 2017 to 2025). A condition of reduced bone mass, with decreased cortical thickness and a decrease in the number and size of the trabeculae of cancellous bone (but normal chemical composition), resulting in increased fracture incidence. "Supportively, ellagic acid has been shown to down-regulate c-FOS expression during osteoclastogenesis, thereby mediating its protective effects against osteoporosis." (PMID 41515139, 2025). "Recent studies have found that whole-brain c-FOS fluorescence quantification can reflect osteoporosis severity." (PMID 41153709, 2025). "As a result, the downregulation of miR-335-3p under chronic psychological stress promotes FOS expression and osteoclast activity, leading to osteoporosis." (PMID 39773351, 2025). "Cnidium lactone regulated osteoporosis by regulating c-FOS/NFATc1 signaling pathways through p38 MAPK and PI3K-Akt." (PMID 36624462, 2023). "It will be worthwhile to further study the roles of PTPN6, CTSD, and FOS in other cells or biological processes except osteoclasts, and explore their significance in the occurrence and development of osteoporosis from the perspective of proteomics and protein modification omics." (PMID 35095774, 2021). "Previous studies have shown that inhibition of FOS in Raw264.7 cells can inhibit RANKL-induced osteoclastogenesis, which may be an effective way to treat osteoporosis." (PMID 36624462, 2023). "Interestingly, IL-6 receptor levels have been reported to reflect OSA severity; FOS, FOSB, and JUN have been demonstrated to be involved in obesity, osteoporosis, and colorectal cancer; and DUSP1 is upregulated in CIH in OSA patients." (PMID 36468038, 2022).
colorectal cancer (29 papers, 2008 to 2025). A primary or metastatic malignant neoplasm that affects the colon or rectum. "PCIF1 controls the stability of FOS mRNA in colorectal cancer cells through m6Am deposition, thereby regulating TGF-β transcription." (PMID 37779183, 2023). "Exogenous SYNPO2 can inhibit the occurrence and development of colorectal cancer by upregulating the expression of Proto-Oncogene C-Fos (FOS) and its downstream factors." (PMID 37544991, 2023). "Wang found that FOS is a downstream target gene of m6Am modification in colorectal cancer." (PMID 37779183, 2023). "JUN and FOS were involved in lots of pathways, including MAPK signaling pathway, PD‐L1 expression and PD‐1 checkpoint pathway in BC, colorectal cancer, and even coronavirus disease––COVID‐19 pathway." (PMID 35037412, 2022). "In colorectal cancer, phosphorylated CTD interacting factor 1 (PCIF1) modulates colorectal cancer growth and response to anti-programmed cell death 1 (PD-1) in a context-dependent mechanism in which PCIF1 directly targets FOS, IFITM3, and STAT1 via N6,2′-O-dimethyladenosine (m6Am) modifications." (PMID 40681213, 2025). "Notably, conserved overexpression of JUN/FOS (AP-1 complex) and ITGB1 was observed across all three cancer types and colorectal cancer, underscoring their roles as shared molecular drivers." (PMID 40725477, 2025). "Here, we revealed that DSF activates autophagy in colorectal cancer (CRC) cells via dual mechanisms: compensatory autophagy induction through proteasome inhibition by targeting the p97-NPL4 axis, and transcriptional upregulation of the autophagy-related gene BECN1 via FOS gene activation." (PMID 41387670, 2025).
hepatocellular carcinoma (29 papers, 2008 to 2026). A malignant tumor that arises from hepatocytes. "At the same time, some studies have shown that JUN and FOS are closely related to the formation of hepatocellular carcinoma." (PMID 36380355, 2022). "Studies on human hepatoma cell lines have shown that c-FOS plays an essential role in cell migration." (PMID 35677538, 2022). "It has also been demonstrated that the expression of FOS is elevated in human hepatoma compared with adjacent tissues." (PMID 32664401, 2020). "MiR-101 was shown to promote apoptosis and suppress FOS oncogene expression in human hepatoma cells and to act as tumor suppressor gene in carcinogenesis of human hepatoma." (PMID 20444294, 2010). "To validate our miRNA-mRNA-pathway interaction network analysis, we examined the expression of FOS, LAMC2, CALML3, and their interacting miRNAs using 20 pairs of hepatocellular carcinoma samples and adjacent normal tissues by RT-PCR." (PMID 32280695, 2020). "Previous studies from hepatocellular carcinomas have suggested that MCL-1 and FOS were regulated by miR-101." (PMID 25153722, 2014). "In the hepatocellular carcinoma cell line Hepa 1–6, overexpression of JUN together with FOS could enhance the activity of MET, which also seems to be a downstream target of PA1." (PMID 35379345, 2022). "Expression of FOS was enhanced in human omental microvascular endothelial cells when incubated with TNF-α for 10 min, whereas BCL3, a nuclear protein primarily found in B lymphocytes, increased when human hepatocellular carcinoma cell lines (HepG2) were stimulated with TNF-α." (PMID 19925655, 2009).
viral infection (29 papers, 2011 to 2026). "A viral infection is envisioned to interact with predisposition networks which include counterpart proteins in various downstream stages (including in the current data set: FOS, ELAVL1, NFkB1, POLR3B, and others at different cellular compartments and stages of the tumorigenesis)." (PMID 26442106, 2015). "Genes down-regulated in the pro-inflammatory monocytes of ACLF patients included FOS, CCL3 and LGALS2, which are mainly associated with resistance to viral infection, promotion of apoptosis, and immunosuppression." (PMID 36626090, 2023). "The expression of FOS during oxidative stress is indicative of its function in signaling pathways that activate inflammatory and immune responses, which are crucial for combating viral infections like Mpox." (PMID 39456924, 2024). "The FOS gene, particularly through its protein product c-Fos (Proto-Oncogene c-Fos), plays a role in regulating gene expression in response to external stimuli, including viral infections." (PMID 39456924, 2024). "Moreover, changes in the human phosphoproteome upon viral infection highlighted several RSK target proteins in addition to c-FOS and EIF4B, such as 40S ribosomal protein S6, Tuberin/TSC2, or GSK347." (PMID 35078976, 2022). "The dysfunctional KSHV genome in FOS expression could be rescued by Lenti-ORF57 virus infection." (PMID 38410462, 2024). "In the context of viral infections, HCV enhances the phosphorylation of JUN and FOS by upregulating the double-stranded RNA-activated protein kinase R (PKR), promoting viral replication." (PMID 40005815, 2025). "FOS and JUN are early response genes whose expression is induced by cell-extrinsic and cell-intrinsic signals like during viral infection." (PMID 35854219, 2022). "For instance, the expression of FOS and MYC oncogenes are induced by growth factors, oxidative stress, dsRNA, and viral infection." (PMID 25004084, 2014). "Based on our data regarding PKR, it would be most reasonable to interpret that nc886 knockdown was a mimicry of viral infection and accordingly induced MYC and FOS as well as genes related to inflammation and infection such as oncogenic NF-κB." (PMID 25004084, 2014). "At the early stages of virus infection i.e. at 4 hpi, we found up-regulation of immune genes like TNF-α3, EGR-1, IL6R, v-FOS, v-JUN." (PMID 21439068, 2011). "Similarly, stress response and apoptosis-related genes FOS, JUN, and activating transcription factor 3 (ATF3) show increased expression in severe cases, highlighting the role of NK cells in modulating cell death pathways in response to viral infection." (PMID 39928675, 2025). "The CD8+ T cell-specific clonotype, however, was only expressed in T cells that had little expression of CD69, FOS and FOSB, suggesting that this was not an active viral infection." (PMID 38665903, 2023). "EGRs, FOS and JUN are immediate early response genes which expression can be rapidly induced without requiring de novo protein synthesis during viral infection." (PMID 31725732, 2019). "Since FOS, FOSB and NR4A1 gene expression was consistently lacking in epithelial transcriptional responses to SARS‐CoV‐2, we next investigated their contribution to viral infection by modulation of their activity, or modulation of related signalling pathways, using small molecules." (PMID 38623540, 2024).
atherosclerosis (27 papers, 2011 to 2025). A disease characterized by the build-up of fatty material and calcium deposition in the arterial wall resulting in partial or complete occlusion of the arterial lumen. "SMC-specific c-FOS deficiency prevents formation of foam cells in vitro and suppresses atherosclerosis in HFD-fed Apoe–/– mice, demonstrating a fundamental proatherogenic role of FOS." (PMID 36602878, 2023). "FOS proteins have been associated with the progression of inflammatory diseases like rheumatoid arthritis, inflammatory bowel disease, endothelial dysfunction, and atherosclerosis." (PMID 39050921, 2024). "FOS has been implicated in the pathogenesis of atherosclerosis and heart disease." (PMID 24558408, 2014). "Although animal models differ from human disease, the magnitude and trans-model consistency of these effects highlight the therapeutic promise of modulating the AKT/c-FOS/IL-6 axis for IL-6-driven chronic inflammatory disorders such as atherosclerosis." (PMID 41515139, 2025). "Mechanistically, FC peel extract inhibits AKT phosphorylation, suppresses c-FOS expression and nuclear translocation, reduces IL-6 transcription and inflammation, and thus alleviates atherosclerosis." (PMID 41515139, 2025). "The core targets correspond to 18 pathways, CXCL8, CY1A2, FOS, and other targets correspond to multiple pathways, and the most corresponding pathway is lipid and atherosclerosis pathway." (PMID 38905402, 2024). "According to an intriguing study, the transcript levels of FOS are the best indicators of the relationship between smoking and MI, offering a possible marker for gauging the severity and progression of atherosclerosis." (PMID 39086489, 2024). "The molecular mechanism analysis revealed that the active components of WGP have a positive influence on the four potentially important therapeutic targets of aging, atherosclerosis, or fatigue (i.e., FOS, ESR1, MAPK8, and SP1)." (PMID 39334763, 2024). "The top three core genes of WGP-atherosclerosis were FOS, ESR1, and MAPK8." (PMID 39334763, 2024). "Similarly, a previous study of the monocyte transcriptome from subjects with atherosclerosis had shown that up-regulation of FOS and DUSP1 was a reliable biomarker of disease severity (especially of the inflammatory state)." (PMID 23185405, 2012). "Though CTA-384D8.35, CTB-114C7.4 and miR-4497 have not been studied yet, their functions could be interpreted by their target genes in the ceRNA network, including inflammatory responses (CCL3, ZFP36, IER3), apoptosis (EGR1), atherosclerosis and myocardial ischemia (FOS)." (PMID 31443660, 2019). "FOS, ESR1, MAPK8, and SP1 are important targets for anti-aging, anti-atherosclerosis, and anti-fatigue." (PMID 39334763, 2024). "The FOS/MAPK signaling pathway inhibits M1 macrophage polarization and promotes M2 polarization, inhibiting and stabilizing the progression of atherosclerosis plaques." (PMID 39334763, 2024). "ST analysis showed that IGF-1 suppressed FOS/FOSB factors and gene expression of MMP9 and CXCL14 in plaque macrophages, suggesting possible involvement of these molecules in IGF-1’s effect on atherosclerosis." (PMID 36602878, 2023). "ST analysis revealed that IGF‐1 inhibited gene expression of FOS/FOSB factors, as well as MMP9 and CXCL14 in plaque macrophages, these molecules may be involved in the IGF‐1 effect on atherosclerosis." (PMID 40156163, 2025). "The top three WGP ingredients (quercetin, EGCG, and kaempferol) could bind stably to the top four core genes of aging, atherosclerosis, and fatigue (FOS, ESR1, MAPK8, and SP1), except that EGCG could not dock successfully with SP1." (PMID 39334763, 2024).
epilepsy (27 papers, 2014 to 2025). A brain disorder characterized by episodes of abnormally increased neuronal discharge resulting in transient episodes of sensory or motor neurological dysfunction, or psychic dysfunction. "We focused on three genes relevant for seizures and epilepsy: FOS proto-oncogene (c-Fos), inducible cAMP early repressor (Icer) and mammalian target of rapamycin (mTor)." (PMID 33859552, 2021). "FOS is an immediate early gene, and it is rapidly expressed under the induction of such factors as hypoxia, trauma, and epilepsy." (PMID 33062018, 2020). "Some studies suggested that miR-129 could suppress c-FOS expression by inhibiting MAPK signaling pathway and thus hinder the occurrence and development of epilepsy." (PMID 34383804, 2021).